PRR36 (proline rich 36)
Tractability: PROTAC: its protein half-life has been measured.
Gene: Protein-coding gene on chromosome 19 (7,868,719 to 7,874,390, reverse strand). Ensembl gene ENSG00000183248.
Subcellular location (Human Protein Atlas): Golgi apparatus; Nuclear speckles; Nucleoplasm
Genetic constraint (gnomAD): Loss-of-function variants: 28 observed, 41.84 expected, observed/expected ratio (o/e) 0.67, 90% interval 0.5 to 0.92. The upper end of that interval is the gene's LOEUF score, 0.92, which puts it in group 3 of 6, group 1 being the genes least tolerant of losing a copy. Missense variants: 1,587 observed, 1,416 expected, observed/expected ratio (o/e) 1.12, 90% interval 1.08 to 1.17. Synonymous variants: 720 observed, 645.88 expected, observed/expected ratio (o/e) 1.11, 90% interval 1.05 to 1.19.
Homologues: Orthologues: chimpanzee PRR36 (93% identical), macaque PRR36 (91% identical), dog PRR36 (57% identical), rat Prr36 (49% identical), mouse Prr36 (48% identical), tropical clawed frog prr36 (23% identical), zebrafish prr36a (16% identical). Paralogues in human: BTBD8 (15% identical).
Diseases named in the same sentence as PRR36 in open-access papers:
PRR36 is named in the same sentence as 1 disease in open-access papers, as found by Europe PMC text mining. Sharing a sentence is not in itself a finding about the gene and the disease. The quoted sentences say what the papers report.
schizophrenia (1 paper, 2017). A major psychotic disorder characterized by abnormalities in the perception or expression of reality. "Based on our analysis for the S-TOGET trio data, three genes in this region, including EVI5L, PRR36, and LYPLA2P2, were detected to be associated with schizophrenia at the suggestive significance level of 5 × 10−5." (PMID 29066733, 2017). "Three genes on chromosome 19p13.2, including EVI5L (ecotropic viral integration site 5 like), PRR36 (proline rich 36), and LYPLA2P2 (lysophospholipase II pseudogene 2), were detected to be associated with schizophrenia at the suggestive significance level of 5 × 10−5." (PMID 29066733, 2017).